IL5 (interleukin 5)
Diseases named in the same sentence as IL5 in open-access papers (continued):
Sharing a sentence is not in itself a finding about the gene and the disease.
influenza (43 papers, 2011 to 2025). An acute viral infection of the respiratory tract, occurring in isolated cases, in epidemics, or in pandemics; it is caused by serologically different strains of viruses (influenzaviruses) designated A, B, and C, has a 3-day incubation period, and usually lasts for 3 to 10 days. "Influenza encodes PB1-F2, a protein that represses ILC2 IL-5 responses, leading to decreased tissue integrity and survival, suggesting that influenza has evolved immune evasion mechanisms that target ILC2s." (PMID 38684766, 2024). "IL-4 and IL-5 have been associated with positive outcomes to infection by Hepatitis B virus and influenza and aid in the clinical recovery of experimental autoimmune encephalomyelitis (EAE) models of multiple sclerosis." (PMID 35805128, 2022). "Moreover, mice deficient in IFNγ show decreased immunopathology in response to influenza infection, which is associated with increased IL-5 production by ILC2s, suggesting that ILC2s protect against immunopathology." (PMID 38684766, 2024). "Induction of influenza‐specific IgG antibodies was compared for IL‐5‐ and placebo‐vaccinated horses and showed comparable results, even in horses being IL‐5 vaccinated in two subsequent years." (PMID 40838325, 2025). "For IL‐5‐vaccinated horses, we included horses that have received an influenza vaccination after IL‐5 immunity was established; and included 1st (basic vaccination after prime‐boost schedule) and 2nd (booster) years of eIL‐5‐CuMVTT‐vaccinated horses." (PMID 40838325, 2025). "Some of the cytokines were very low in the PBS group, especially the signatures for T-cell responses such as IL-4, IL-5, and IL-13, which is in line with the typical type 1 skewed host immune response to influenza infection." (PMID 38711520, 2024). "In contrast, splenocytes isolated from mice vaccinated against influenza vaccination that were exposed to acidic oligosaccharide ex vivo had lower secretion of Th2 cytokines (IL-4, IL-5, and IL-10)." (PMID 38179055, 2023). "For example, it reported that IL-28B is an important regulator of the Th1/Th2 balance by increasing Th1-type cytokines (IFN-γ) and decreasing Th2-type cytokines (IL-4, IL-5 and IL-13) during influenza vaccination." (PMID 34818327, 2021). "In a subset of individuals, the bacterially produced recombinant VLP-based influenza vaccine shifted pre-vaccination-induced type-2 cytokines such as IL-5 and IL-13 to a post-vaccination type-1 cytokine signature characterized by IFN-γ." (PMID 33800349, 2021). "It has previously been demonstrated that iNKT cells activate ILC1s to secrete IFNγ and stimulate ILC2s to produce IL5 during influenza infection in the lung." (PMID 33513946, 2021). "In these experiments, anti‐IL‐5 treatment prevented eosinophil influx and influenza‐induced exacerbation of airway inflammation." (PMID 29762870, 2019). "Furthermore, IL-5 derived from lung ILC2 following influenza infection has been implicated in the recruitment and accumulation of eosinophils following viral clearance, even though the roles of eosinophils in promoting tissue repair or host pathology in this context are unknown." (PMID 30893756, 2019). "The accumulation of eosinophils during the recovery phase of influenza infection seemed to suggest a potential role for IL-5 (and eosinophils) in the pulmonary repair process." (PMID 31415658, 2019). "Neutrophils from the lungs of 10 d.p.i. α-IL-5-treated mice produced significantly more ROS than 10 d.p.i. neutrophils from control IgG treated influenza infected animals." (PMID 31415658, 2019). "Fatty acid uptake and IL‐5 production remained lower in aged lung ILC2 after influenza infection than those in young lung ILC2." (PMID 31429526, 2019). "Overall, when we compared the relative contribution of CD4+ T cells and ILC2s to the population of type 2 cytokine expressing cells, it was apparent that CD4+ T cells were the major source of IL‐5 or IL‐13 in the early phase of influenza‐induced exacerbation." (PMID 29762870, 2019).
influenza (continued). "This capacity of the gH1-Qbeta vaccine to preferentially elicit IFN-γ is seen in a subset of individuals whose pre-existing influenza-specific cytokine responses were characterized by the T helper type 2 (Th2) cytokines IL-5 and IL-13." (PMID 30573748, 2018). "We found an increase in the levels of the inflammatory cytokines IL-1α, IL-1β, TNFα, IL-6, IL-12p40, IL-17, and IFNγ, and increased levels of the Type 2 cytokines IL-4 and IL-5, in influenza-infected Stat2−/− mice when compared to WT mice." (PMID 30337919, 2018). "SOCS1−/−IFN-γ−/− mice exhibited significantly decreased production of IL-6 and IL-10 at 7 dpi but increased IL-4, IL-5 and IL-13 levels in airways during influenza infection." (PMID 25500584, 2014). "Here we show that IL-5 is produced in response to influenza infection and results in the progressive accumulation of eosinophils in the lung." (PMID 24068930, 2013). "Taken together these data suggest that IL-5 not only continues to be produced in the influenza-infected lung during the recovery phase, but also is responsible for the progressive accumulation of eosinophils in the lungs." (PMID 24068930, 2013). "Only the CW 1064 nm laser also significantly increased influenza-specific CD4+IL-5+ T-cell subpopulations (P<0.003)." (PMID 24349390, 2013). "In the current study we focused on defining the cellular source of IL-5 in the influenza-infected lungs and the tempo of IL-5 protein and gene expression." (PMID 24068930, 2013). "Here, pulmonary VV inoculation mirrored influenza infection as pulmonary transcripts for IL-5, IL-13, and IL-17 were significantly decreased in VV-infected mice with AAD." (PMID 23620814, 2013). "To investigate whether IL‐5 vaccination affected the immune system's ability to perform class switching of antibodies, we compared levels of influenza IgG antibodies in placebo and IL‐5‐vaccinated horses." (PMID 40838325, 2025). "The production of IL-5 in response to influenza infection stimulates the accumulation of eosinophils in the lungs, which can cause eosinophilic pneumonia acutely but may also contribute to the clearance of virus." (PMID 35145069, 2022). "Our curation indicates that the cytokine response induced by SARS-CoV-2 is different compared to other CRS-causing respiratory viruses, as SARS-CoV-2 does not always induce specific cytokines like other coronaviruses or influenza do, such as IL-2, IL-10, IL-4, or IL-5." (PMID 33732251, 2021). "Pediatric influenza patients who developed acute pneumonia demonstrated a rise in the serum IL-5 levels and peripheral eosinophilia, suggesting that eosinophil recruitment may be necessary for late-stage anti-influenza host defense." (PMID 31612153, 2019). "However, NMRI mice receiving WIV and N3 with pFliC(-gly) had a significantly lower secretion of IL-5 production after influenza antigen restimulation." (PMID 31315253, 2019). "The ability of the gH1-Qbeta VLP vaccine to influence the quality of the cytokine response was further emphasized in specific individuals whose pre-existing influenza responses were characterized by a higher level of the Th2 cytokines IL-5 and IL-13 over the Th1 cytokine IFN-γ." (PMID 30573748, 2018). "We show that a newly discovered cell type, the group 2 innate lymphoid cell (ILC2), is responsible for IL-5 production during influenza infection and that the capacity of ILC2 to make IL-5 is greatly increased following virus clearance, i.e. during the recovery phase." (PMID 24068930, 2013). "As potent producers of IL-5, ILC2s may regulate eosinophil infiltration during influenza." (PMID 31612153, 2019).
influenza (continued). "To determine whether ILC2 can produce IL-5 following influenza infection in vivo, we first analyzed IL-5 production and the contribution of ILC2 as a source of IL-5 in adaptive immune cell deficient, IAV infected Rag2-/- mice since the majority of Thy1.2+ cells in these mice are ILC2." (PMID 24068930, 2013). "To control for B cells being not generally impaired in their ability to perform Ig class switching caused by an IL‐5‐vaccine‐induced lack of IL‐5 and a consequently interlinked lack of IL‐4, we investigated the ability of IL‐5‐vaccinated horses to respond to a seasonal influenza vaccine." (PMID 40838325, 2025). "Administration of the novel virus-like particle based vaccine elicited influenza-specific CD4+ and CD8+ T-cell responses and the induction of the cytokines IFN-γ, IL-17A, IL17F, IL-5, IL-13, IL-9, IL-10 and IL-21." (PMID 30573748, 2018). "Collectively, these results reveal that c-kit+ ILC2 interaction with IL-33 producing NKT and AM leads to abundant production of IL-5 by ILC2 and accounts for the accumulation of eosinophils observed during the recovery phase of influenza infection." (PMID 24068930, 2013). "While an RSV infection of allergic animals results in enhanced Th2 cytokine production in the lungs, influenza respiratory challenge of AAD mice reduced lung IL-4, IL-5, and IL-13 expression." (PMID 23620814, 2013). "The production of IL-5 by ILC2 is in part regulated by NKT cells and IL-33 produced by this cell type during the recovery phase of influenza infection." (PMID 24068930, 2013). "Pandemic influenza vaccines should preferentially activate both Th1 (IL-2, IFN-γ and TNF-α) and Th2 subsets (IL-4, IL-5, and IL-10) of T helper cells, since both are important for elimination of influenza virus from the host." (PMID 22069479, 2011). "Interestingly, we saw a positive correlation between IL-5 and the adaptive immune response; we have previously observed this to an MF59 formulated influenza vaccine." (PMID 37876532, 2023). "Cytokines such as IL-4, IL-5, IL-6, IL-8, IL-13, and TNF-α, chemokines such as CCL2 and CCL3, and the MC proteases tryptase and chymase can be detected in the supernatants of influenza infected MC cultures and in the bronchioalveolar lavage fluid (BALF) of both influenza patients and infected mice." (PMID 33680987, 2021). "Summarizing the cell-mediated immune responses that were obtained at day 90, prior to influenza virus challenge, suggest that the used adjuvants were all capable of supporting both influenza-antigen stimulated IFN-γ secreting and IL-5 secreting immunity in vitro." (PMID 31315253, 2019). "In addition, IFN-λ increases influenza-induced Th1 cytokines (IFN-γ, IL6), whereas influenza-induced Th2 cytokines decrease (IL4, IL5, IL9, IL13)." (PMID 28293236, 2017). "To determine the possible impact of ST2 on pulmonary inflammation during influenza infection, we measured lung levels of cytokines (IFN-γ, TNF-α, IL-1β, IL-6, IL-10, IL-33, IL-13, IL-5) and chemokines (KC, MIP-2) at 3, 8 and 14 days following influenza inoculation." (PMID 23483993, 2013). "During respiratory virus infection, such as influenza infection, IL-5 and eosinophils are not thought to play a major role in host defense." (PMID 24068930, 2013). "TNFα remained below the limit of detection during influenza infection, whereas IL-5 and IL-13 were not induced by influenza infection (data not shown)." (PMID 23483993, 2013). "IL-5 beneficial effects on a mouse model of influenza do not depend only on eosinophils." (PMID 33767626, 2021). "Additionally, influenza nanoparticle constructs significantly upregulated the levels of chemokines (IL-8, MCP-1 and MIP-1β) as well as the Th1- and Th2- related cytokine productions (IFN-γ and IL-5)." (PMID 32760143, 2020).
influenza (continued). "In addition, these children received an influenza vaccine and similarly it was found that the IFN-γ response to influenza was higher in non-infected children, whereas IL-5 and IL-13 production was increased in infected children." (PMID 23272112, 2012). "In striking contrast, NKT cells represent up to 50%–70% of the total IL-4+ cells after influenza infection; however, we did not detect NKT cell production of other type 2 cytokines, such as IL-5 and IL-13." (PMID 29249358, 2018).
hypereosinophilic syndrome (41 papers, 2013 to 2026). Hypereosinophilic syndrome (HES) constitutes a rare and heterogeneous group of disorders, defined as persistent and marked blood eosinophilia and/or tissue eosinophilia associated with a wide range of clinical manifestations reflecting eosinophil-induced tissue/organ damage. "Hypereosinophilic syndrome (HES) is a kind of disorder characterized by eosinophilia associated with increased responsiveness to IL-5." (PMID 34502451, 2021). "Anti-interleukin-5 antibody therapy has demonstrated efficacy in reducing eosinophil counts and enabling steroid dose tapering in patients with hypereosinophilic syndrome." (PMID 40382631, 2025). "Mepolizumab, an anti-interleukin (IL)-5 monoclonal antibody, is approved for use in hypereosinophilic syndrome (HES), a group of disorders characterized by peripheral eosinophilia and eosinophil-induced organ dysfunction." (PMID 39430638, 2024). "IL-5 plays a crucial role in eosinophilic pathophysiology and is proposed as a novel therapeutic target for hypereosinophilic syndrome and rare eosinophilic conditions." (PMID 37187735, 2023). "A humanized monoclonal anti-IL-5 has been evaluated for treatment of hypereosinophilic syndromes that affects fibrogenesis." (PMID 34983483, 2022). "Studies with the anti‐IL‐5 antibody mepolizumab have demonstrated efficacy for the treatment of hypereosinophilic diseases." (PMID 33624312, 2021). "Antibodies blocking IL-5 and IL-5 receptor have been approved for asthma and have successfully been tested in hypereosinophilic syndromes." (PMID 34097126, 2021). "A hypereosinophilic syndrome was diagnosed in five cases and a solid tumor IL-5 expression in five cases." (PMID 30256812, 2018). "Additional therapeutic options in CEL-NOS include Mepolizumab, an investigational anti-IL5 antibody that has shown activity in patients with hypereosinophilic syndrome." (PMID 27746819, 2016). "Notably, in hypereosinophilic syndrome, where IL-5 levels are elevated, Morrbid expression in eosinophils correlates positively with plasma IL-5, suggesting a role in cytokine-driven eosinophil persistence in inflammatory diseases." (PMID 40722500, 2025). "IL-5/5R targeting MAbs, such as mepolizumab and benralizumab, which have shown favorable safety profiles and effectiveness in both clinical trials and real-world settings, including patients with hypereosinophilic syndrome." (PMID 40508151, 2025). "However, IL-5 elevations have also been observed with higher doses of mepolizumab (750 mg) and with other “hypereosinophilic” diseases, such as hypereosinophilic syndrome and eosinophilic esophagitis." (PMID 35055384, 2022). "Finally, with increasing use of anti-IL-5 or anti-IL-5R antibodies for hypereosinophilic disease in clinical practice, in the near future the focus should be on optimizing doses and regimens." (PMID 33418988, 2021). "Conversely, the etiology of other reactive eosinophilias remains largely unknown, apart from “lymphoid variant of hypereosinophilic syndrome” (L-HES) in which chronic eosinophilia is associated with a minority of circulating T cell clone and high IL-5 levels." (PMID 28546866, 2017). "Therapies include corticosteroids, immunosuppressants and Mepolizumab, an anti-IL-5 drug directed against type 2 (T2)-eosinophilic inflammation previously approved for the treatment of severe eosinophilic asthma and recently approved also for severe CRSwNP, hypereosinophilic syndrome (HES) and EGPA." (PMID 38090592, 2023). "Mepolizumab is an anti-IL-5 humanized IgG1κ antibody that is FDA-approved for the treatment of severe eosinophilic asthma, hypereosinophilic syndrome, and eosinophilic granulomatosis with polyangiitis (EGPA)." (PMID 37187735, 2023). "Monoclonal antibodies against IL-5 (mepolizumab, reslizumab) and IL-5R (benralizumab) have been reported to dramatically decrease blood eosinophil counts in asthma patients and in patients with hypereosinophilic syndrome (HES)." (PMID 37555911, 2023).
hypereosinophilic syndrome (continued). "Anti-IL-5 therapy is an effective way to manage hypereosinophilic syndrome (HES) patients." (PMID 29160801, 2017). "Because cytokine priming occurs in vivo in a variety of allergic, parasitic and other hypereosinophilic disorders, and because eosinophils die rapidly without survival factors, cultures were performed in the presence of IL-5." (PMID 24727794, 2014). "Mepolizumab was the first registered (in 2004) anti–IL-5 biologic for the treatment of severe eosinophilic asthma (SEA), before validation in other conditions including CRSwNP, hypereosinophilic syndrome (HES), and eosinophilic granulomatosis with polyangiitis (EGPA)." (PMID 37035303, 2023). "The doses of anti-IL-5/Rα biologics used in our study were those used in severe eosinophilic asthma, and only one patient received mepolizumab 300 mg, the approved and recommended regimen to treat relapsing or active, non-severe EGPA, or the hypereosinophilic syndrome." (PMID 38585151, 2024).